GDF15 (growth differentiation factor 15)
Diseases named in the same sentence as GDF15 in open-access papers (continued):
Sharing a sentence is not in itself a finding about the gene and the disease.
Myocardial fibrosis (25 papers, 2018 to 2025). "It has been shown that ghrelin improves myocardial fibrosis through GDF15, which is expected to be an effective target for the treatment of myocardial fibrosis." (PMID 39569809, 2024). "TMAO and betaine were also significantly associated with myocardial fibrosis measures, and elevated TMAO correlated with cardiac and MT markers like sCD14, NT‐proBNP, troponin‐I, galectin‐3, GDF‐15, and IL‐6." (PMID 39652612, 2024). "It has also been found that GDF15 levels were positively correlated with myocardial fibrosis and the levels of PICP and PIIINP, markers for the synthesis of collagen type I and III." (PMID 32374790, 2020). "Accordingly, latest studies have also demonstrated a correlation between GDF-15 and atrial and myocardial fibrosis along with a prognostic impact in cardiovascular disease." (PMID 32326570, 2020). "Recent studies evaluated the role of GDF-15 as a biomarker of myocardial fibrosis in patients with NIDCM, its correlations with worsening functional capacity in idiopathic dilated cardiomyopathy and its role for risk stratification of arrhythmic death in NIDCM." (PMID 34073616, 2021). "The elevation might be attributed to the progressive myocardial fibrosis and remodeling involved in this disease entity, which could act as a trigger for the secretion of GDF-15." (PMID 32326570, 2020). "Our group has demonstrated in vivo that GDF-15 could enhance the proliferation of fibroblasts and may participate in the progression of myocardial fibrosis." (PMID 32904560, 2020). "Sjoukje I Lok found that growth differentiation factor 15 (GDF) levels are increased in patients with HF and correlate with the extent of myocardial fibrosis, hence they are used as a biomarker for cardiac remodeling." (PMID 36902588, 2023). "For example, high-sensitivity C-reactive protein (hs-CRP) mainly reflects systemic inflammatory states, while GDF-15 is involved in cellular stress responses, and JUP may be more focused on cell connection stability and myocardial fibrosis." (PMID 40433126, 2025). "Although circulating cardiac biomarkers are not specific to myocardial fibrosis, previous studies have noted a positive association between ECV and NT-proBNP, hsTnT and GDF-15." (PMID 40517266, 2025). "In a rat model of HF, lentiviral-mediated silencing of GDF15 triggered myocardial fibrosis [increased α-smooth muscle actin (α-SMA) and excessive collagen deposition] compared to control, suggesting that GDF15 preserves cardiac function by inhibiting fibrosis progression." (PMID 40565178, 2025). "It is assumed that GDF-15 is overexpressed in the presence of enhanced activity of transforming growth factor β (TGF- β), the latter playing a key role in myocardial fibrosis, via fibroblast activation, with subsequent deposition of type III collagen fibers in the extracellular matrix (ECM)." (PMID 36556311, 2022).
liver diseases (24 papers, 2011 to 2026). "Growth differentiation factor‐15 (GDF‐15), a cell stress‐induced cytokine, is implicated in liver disease pathophysiology." (PMID 41555670, 2026). "In liver disease, the role of GDF‐15 is unclear, with prior findings showing both protective effects and associations with more pronounced liver disease severity and worse outcomes." (PMID 41555670, 2026). "Higher GDF‐15 levels remained independently linked to the risk of all‐cause mortality in multivariable models adjusted for age and liver disease‐driving parameters." (PMID 41555670, 2026). "In this study, we investigated the association between GDF‐15 and liver disease‐driving mechanisms in patients with cirrhosis." (PMID 41555670, 2026). "In our well‐characterised prospective cohort, we found that GDF‐15 is linked to fibrogenesis and bacterial translocation and predicts disease progression and mortality independently of hepatic dysfunction and portal hypertension." (PMID 41555670, 2026). "GDF‐15 is induced by cellular stress and inflammation and has been implicated in the pathogenesis and progression of various chronic diseases, including liver disease." (PMID 41555670, 2026). "In the current study, we show that alcohol and CCl4-induced liver inflammation and fibrosis are more severe in GDF15 KO mice, which suggests a causal relationship between GDF15 and liver disease." (PMID 29222479, 2017). "Given its broad regulatory effects, increasing attention has turned to the role of GDF‐15 in liver disease, yet its mechanistic impact remains incompletely understood." (PMID 41555670, 2026). "Our results corroborate these findings, linking GDF‐15 to hepatic dysfunction, portal hypertension severity, liver stiffness, and fibrogenesis." (PMID 41555670, 2026). "Higher GDF‐15 levels correlated with more pronounced liver disease severity, portal hypertension, systemic inflammation, liver stiffness, and fibrogenesis." (PMID 41555670, 2026). "Lastly, despite our analyses of potential pathophysiological implications of GDF‐15, further research is required to fully elucidate its cellular origin and molecular function in liver disease and fibrosis." (PMID 41555670, 2026). "On the other hand, preclinical data suggest GDF‐15 ameliorates liver disease progression by decreasing the expression of proinflammatory cytokines and suppressing genes related to fibrogenesis." (PMID 41555670, 2026). "Despite the observed preclinical effects of GDF‐15 in liver disease, insights into prognostic implications are scarce." (PMID 41555670, 2026). "It is clear that paediatric mitochondrial diseases demonstrate GDF15 elevation, greatest in patients with hepatic disease." (PMID 40019842, 2025). "The consistent upregulation of Trem2, Anxa2, Ttc39a, and Gdf15 across all stages of liver disease—from steatosis and NASH to fibrosis—suggests that these genes play a pivotal role in the progression of NAFLD." (PMID 39697329, 2024). "GDF15, a stress-responsive cytokine, plays a critical role in liver disease progression, especially in NAFLD and fibrosis." (PMID 39697329, 2024). "We found that serum GDF15 levels were significantly higher in patients with AIH than in those with other liver diseases." (PMID 35610317, 2022). "Growth differentiation factor 15 (GDF15) has been reported to be associated with fibrosis and cancer in liver disease." (PMID 35610317, 2022). "Accordingly, it was possible to determine the relationship between liver disease and GDF15 more simply and clearly." (PMID 35610317, 2022). "B2M, CEA, GDF15, IGFBP2, OPN and PDGF-Rb, which are uncertain about the association with liver cancer but have involvement in liver diseases or multiple cancers; 3)." (PMID 30220970, 2018). "Nevertheless, the role of GDF15 in alcohol-induced or fibrotic liver diseases has yet to be determined." (PMID 29222479, 2017).
liver diseases (continued). "In the present study, a large multicenter evaluation was conducted to compare the serum GDF15 levels in healthy subjects and patients with hepatitis virus-related liver diseases." (PMID 25996938, 2015). "In this study, to investigate the potentially indicative role of GDF15 in severe liver diseases, 202 healthy subjects, 223 patients with HCC and 88 patients with LC were recruited between 2010–2011." (PMID 25996938, 2015). "This study aimed to investigate GDF15 expression and its correlation with hepatitis virus-related liver diseases." (PMID 25996938, 2015). "In the HCV-infected patients, we tried to assess the possible relationship between serum GDF15 levels and several disease characteristics, including viral load, genotypes and liver disease progression." (PMID 21625435, 2011). "Beyond the association between GDF‐15 and liver disease severity, we did not observe a significant link to platelet activation." (PMID 41555670, 2026). "Platelet activation was not linked to GDF‐15 after adjusting for liver disease severity, yet patients with undetectable GPIIb/IIIa activation after stimulation showed significantly higher GDF‐15." (PMID 41555670, 2026). "Prognostically, elevated GDF‐15 levels predicted hepatic decompensation and mortality independently of the severity of liver disease and portal hypertension and could therefore be used for personalised treatment decisions." (PMID 41555670, 2026). "Indeed, GDF15 secretion is stimulated by hypoxia, chronic inflammatory disease, chronic kidney, and liver disease." (PMID 41303556, 2025). "Specifically, GDF15 was useful to distinguish autoimmune hepatitis from other liver diseases and a recent study showed that patients with autoimmune hepatitis were GDF15 positive after immunohistological staining in the hepatic cytoplasm and sinusoidal endothelial cells." (PMID 41303556, 2025). "Specific HIV‐related risk factors (e.g., effects of persistent viral factors such as Vpr, immune activation, and antiretroviral drugs) may result in an altered course of liver disease and sustained GDF15 secretion." (PMID 35510313, 2022). "We hypothesize that the multi-xenobiotic-responsive lnc7169 has a role in regulating these beneficial Gdf15-dependent hepatic disease-related processes." (PMID 33761883, 2021). "Although future studies should be performed to elucidate the mechanism of cellular GDF15 induction and secretion in damaged hepatocytes, GDF15 could be a novel therapeutic target for the treatment of liver diseases." (PMID 29222479, 2017). "Therefore, to determine the effect of GDF15 on advanced liver disease, we used the CCl4-induced model of liver injury." (PMID 29222479, 2017). "The link between serum levels of GDF15 and liver disease is well described in mice and in humans, but it remains to be determined whether GDF15 has direct effects on hepatic inflammation and fibrosis." (PMID 29222479, 2017). "Furthermore, in contrast to findings in cardiovascular research, we did not observe a significant association of GDF‐15 with bleeding events after accounting for portal hypertension severity, as most events were classified as portal hypertensive bleeding." (PMID 41555670, 2026). "However, further large-scale cohort studies with a prospective longitudinal design and unraveling the causal relationship between GDF15 and fibrosis progression are warranted to confirm the clinical usefulness of GDF15 as a novel biomarker for predicting advanced fibrosis in liver diseases." (PMID 40565178, 2025). "Collectively, these data highlight the complex relationship between inflammatory mediators and liver diseases, positioning GDF-15 and HMGB1 as central mediators of hepatic and systemic inflammation in PALF and further recasting MIG as a chemokine that may help control inflammation." (PMID 40809145, 2024). "Furthermore, the role of GDF15 in liver disease extends beyond a simple marker of disease severity." (PMID 39697329, 2024).
liver diseases (continued). "More recently, elevated levels of GDF-15 were reported in children diagnosed with mitochondrial hepatopathy (MH), including some with the PALF phenotype, compared to other childhood liver diseases." (PMID 40809145, 2024). "Growth differentiation factor 15 (GDF15) is a mitokine, the role of which, total or H-specific, in modulating energy metabolism and homeostasis in obesity-related diseases, such as metabolic dysfunction associated steatotic liver disease (MASLD), has not been fully elucidated in adult humans." (PMID 38762719, 2024). "Hopefully, approaches that specifically target GDF15 signaling will suppress HCV infection and the severity of liver disease." (PMID 21625435, 2011). "Both in human patients and animal models, GDF15 expression was shown to be decreased in the fibrotic/cirrhotic liver compared with those without liver disease." (PMID 40565178, 2025). "GDF15 levels were higher in non-survivors than in survivors and were significantly lower in healthy children and patients with other liver diseases." (PMID 40260391, 2025). "In comparison among the patient groups, the EPI, NE, and GDF15 levels were much higher in alcoholics without liver disease (AWLD) than in those with AFL and ASH." (PMID 36631664, 2023). "The high serum GDF15 level might be due to more severe liver inflammation and prominent liver regeneration in AIH than in other liver diseases." (PMID 35610317, 2022). "Although the GDF15 receptor and the signaling pathways that drive its biological action have not been unequivocally elucidated, GDF15 is currently considered a reliable biomarker for liver disease, cardiovascular disease, and cancer." (PMID 29222479, 2017). "Notably, the induction of GDF15 in both HCV and HBV infected patients suggests that GDF15 probably is a non-specific liver injury responsive cytokine in viral hepatitis and other hepatic diseases." (PMID 21625435, 2011). "GDF15 expression is also increased in the livers of mice with alcohol feeding or human subjects with alcoholic steatohepatitis (ASH), suggesting that GDF15 may be a biomarker for common liver diseases." (PMID 32225108, 2020). "This study showed that serum GDF15 levels were higher in patients with AIH, especially those with non-cirrhosis, than in those with other liver diseases, and the ROC analysis found that serum GDF15 levels could be a diagnostic marker for AIH." (PMID 35610317, 2022). "As is the case for GDF-15, elevated circulating levels of FGF-21 does not specifically point to a diagnosis of mitochondrial disorders but can also be observed in other conditions, most notably in liver disorders." (PMID 36361969, 2022).
Cognitive impairment (22 papers, 2016 to 2026). Abnormal cognition is characterized by deficits in thinking, reasoning, or remembering. "The strong association between GDF15 levels and cognitive impairment severity suggests its potential as a biomarker for the early detection and monitoring of NCI in PWH." (PMID 39851417, 2025). "Consistent with this, other examinations showed increased peripheral GDF15 was associated with white matter hyperintensities and that this was strengthened in cohorts with cognitive impairment relative to cognitively normal individuals." (PMID 39737171, 2024). "In older subjects, high systemic GDF15 was associated with lower global cognition, worse cognitive performance and cognitive impairment." (PMID 37715843, 2024). "Further study is required to investigate the potential of biomarkers such as GDF15 and NT-proBNP for discriminating risk of cognitive impairment in association with CKD." (PMID 37052588, 2023). "Several studies in mouse models demonstrated that chronic activation of the integrated stress response (ISR), another retrograde stress response sharing many transcription factors with UPRmt and GDF15, can cause cognitive disorders." (PMID 36698863, 2022). "The associations between GDF-15 and cognitive impairment as well as with WMH remained significant after excluding subjects with cardiovascular diseases." (PMID 27537582, 2016). "Furthermore, high GDF15 in older age was associated with cognitive impairment, as well as with lower cognitive function." (PMID 37715843, 2024). "Our data thus extend the previously reported associations between higher peripheral GDF-15 and cognitive impairment in patients with mild cognitive impairment, and further demonstrate that this association is found across the spectrum of cognitive impairment from CIND to AD." (PMID 27537582, 2016). "However, limited data exist on the associations of GDF-15 with either cerebrovascular disease (CeVD) burden or the spectrum of cognitive impairment." (PMID 27537582, 2016). "Recent studies in COPD have identified the aging-related cytokine growth differentiation factor-15 (GDF-15) as a possible mediator linking physical inactivity, mitochondrial stress, and cognitive impairment." (PMID 41440520, 2025). "A serum GDF-15 level > 5408.332 pg/mL exhibited 63.6% sensitivity and 64.4% specificity when distinguishing between normal and mild to severe cognitive impairment, and this was set as the cutoff value." (PMID 38397960, 2024). "(2013) explored possible cross‐sectional and prospective correlations between serum levels of MIC1/GDF15 and cognitive impairment and decline." (PMID 35068064, 2022). "GDF15 levels in patients with cancer, diabetes, cognitive impairment, and cachexia were also identified increasing." (PMID 35068064, 2022). "(2016) concluded that MIC‐1/GDF15 could be used as a marker of age‐related cognitive impairment and brain structural defects." (PMID 35068064, 2022). "The results also indicated that the serum levels of MIC1/GDF15 could be utilized as a potential marker to identify future cognitive impairment." (PMID 35068064, 2022). "Taken together, these results suggest that in subjects with cognitive impairments, GDF-15 has an association with CeVD, which is independent of any potential associations with cardiovascular disease." (PMID 27537582, 2016). "The present study finds that GDF-15 is associated with CIND and AD with CeVD, and may have clinical utility as a peripheral biomarker of WMH-associated cognitive impairments." (PMID 27537582, 2016). "Genes involved in the cognitive impairment MAG, GDF15, GPR176, and EPHB1 (upregulated), BCL11B, GIMAP7, and ACOD1 (downregulated) were differentially expressed." (PMID 38755198, 2024). "Meanwhile, increased GDF15 levels were reported in patients with MSA, AD, and cognitive impairment." (PMID 35068064, 2022).
Cognitive impairment (continued). "The data also suggest that anti-inflammatory interventions may be a rational therapeutic strategy for cognitive impairment and WMH, given that increased GDF-15 may represent responses toward a heightened inflammatory state in the disease brains." (PMID 27537582, 2016).